PHETA2 (PH domain containing endocytic trafficking adaptor 2)
Description:
Plays a role in endocytic trafficking. Required for receptor recycling from endosomes, both to the trans-Golgi network and the plasma membrane.
Synonyms: Ses2; IPIP27B; FAM109B; DKFZp686J07229
Tractability: No criterion of Open Targets' tractability assessment is met for any kind of drug.
Gene: Protein-coding gene on chromosome 22 (42,073,789 to 42,079,439, forward strand). Ensembl gene ENSG00000177096.
Subcellular location: Early endosome; Recycling endosome; Golgi apparatus, trans-Golgi network; Cytoplasmic vesicle, clathrin-coated vesicle
Gene Ontology:
Molecular function: protein binding; protein homodimerization activity
Biological process: endosome organization; receptor recycling; retrograde transport, endosome to Golgi
Cellular component: clathrin-coated vesicle; early endosome; recycling endosome; trans-Golgi network; cytosol; Golgi apparatus
Genetic constraint (gnomAD): Loss-of-function variants: 7 observed, 4.51 expected, observed/expected ratio (o/e) 1.55, 90% interval 0.81 to 1.94. That is too few expected variants to judge how well the gene tolerates losing a copy. Missense variants: 321 observed, 351.82 expected, observed/expected ratio (o/e) 0.91, 90% interval 0.83 to 1. Synonymous variants: 133 observed, 148.93 expected, observed/expected ratio (o/e) 0.89, 90% interval 0.77 to 1.03.
Homologues: Orthologues: chimpanzee PHETA2 (98% identical), macaque PHETA2 (94% identical), pig PHETA2 (84% identical), rabbit PHETA2 (83% identical), guinea pig PHETA2 (80% identical), rat Pheta2 (79% identical), dog PHETA2 (78% identical), mouse Pheta2 (78% identical), zebrafish pheta2 (28% identical). Paralogues in human: PHETA1 (37% identical), PLEKHJ1 (14% identical).
Diseases named in the same sentence as PHETA2 in open-access papers:
PHETA2 is named in the same sentence as 4 diseases in open-access papers, as found by Europe PMC text mining. Sharing a sentence is not in itself a finding about the gene and the disease.
PHETA2 shares sentences with these, for which no sentence is quoted: Cognitive impairment (1 paper); mental disorder (1); psychiatric disorder (1); schizophrenia (1).